TRIM3 (tripartite motif containing 3)
Description:
E3 ubiquitin ligase that plays essential roles in neuronal functions such as regulation of neuronal plasticity, learning, and memory (By similarity). In addition to its neuronal functions, participates in other biological processes such as innate immunity or cell cycle regulation. Component of the cytoskeleton-associated recycling or transport complex in neurons, polyubiquitinates gamma-actin, thus regulating neuronal plasticity, learning, and memory (By similarity). Ubiquitinates postsynaptic scaffold GKAP, a neuronal substrate involved in synaptic remodeling and thereby modulates dendritic spine morphology (By similarity). Positively regulates motility of microtubule-dependent motor protein KIF21B (By similarity). Induces growth arrest via its RING-dependent E3 ligase activity and ubiquitinates CDKN1A. Positively regulates TLR3-mediated signaling by mediating 'Lys-63'-linked polyubiquitination of TLR3. In turn, promotes the recognition and sorting of polyubiquitinated TLR3 by the ESCRT complexes.
Synonyms: BERP; RNF22; RNF97; HAC1
Tractability: Small molecule: a structure with a bound ligand is known. PROTAC: ubiquitination databases record sites on it; its protein half-life has been measured.
Gene: Protein-coding gene on chromosome 11 (6,448,613 to 6,474,459, reverse strand). Ensembl gene ENSG00000110171.
Subcellular location: Cytoplasm; Early endosome; Golgi apparatus, trans-Golgi network; Cell projection, dendrite
Subcellular location (Human Protein Atlas): Mitochondria
Pathways (Reactome):
Immune System: Interferon gamma signaling
Gene Ontology:
Molecular function: identical protein binding; protein binding; ubiquitin protein ligase activity; metal ion binding; ubiquitin-protein transferase activity; zinc ion binding
Biological process: neural precursor cell proliferation; positive regulation of toll-like receptor 3 signaling pathway; protein K63-linked ubiquitination; nervous system development; proteasome-mediated ubiquitin-dependent protein catabolic process; protein polyubiquitination; protein ubiquitination
Cellular component: cytoplasm; early endosome; Golgi apparatus; dendrite
Genetic constraint (gnomAD): Loss-of-function variants: 13 observed, 66.66 expected, observed/expected ratio (o/e) 0.2, 90% interval 0.13 to 0.31. The upper end of that interval is the gene's LOEUF score, 0.31, which puts it in group 1 of 6, group 1 being the genes least tolerant of losing a copy. Missense variants: 711 observed, 1,031.8 expected, observed/expected ratio (o/e) 0.69, 90% interval 0.65 to 0.73. Synonymous variants: 406 observed, 419.48 expected, observed/expected ratio (o/e) 0.97, 90% interval 0.89 to 1.05.
Homologues: Orthologues: rabbit TRIM3 (99% identical), guinea pig TRIM3 (99% identical), macaque TRIM3 (99% identical), dog TRIM3 (99% identical), rat Trim3 (99% identical), mouse Trim3 (99% identical), chimpanzee TRIM3 (96% identical), pig TRIM3 (78% identical), zebrafish trim3b (76% identical), tropical clawed frog trim3 (75% identical), zebrafish trim3a (75% identical). Paralogues in human: TRIM2 (67% identical), TRIM71 (34% identical), TRIM56 (24% identical), TRIM33 (18% identical), TRIM24 (17% identical), TRIM66 (16% identical), TRIM9 (15% identical), TRIM67 (15% identical), TRIM37 (14% identical), TRIM46 (14% identical), TRIM28 (14% identical), TRIM65 (12% identical), and 68 more.
Diseases named in the same sentence as TRIM3 in open-access papers:
TRIM3 is named in the same sentence as 32 diseases in open-access papers, as found by Europe PMC text mining. Sharing a sentence is not in itself a finding about the gene and the disease. The quoted sentences say what the papers report.
gastric cancer (18 papers, 2018 to 2025). A primary or metastatic malignant neoplasm involving the stomach. "We investigated the functional roles of TRIM3 in gastric cancer by using gain- and loss-of-function studies." (PMID 30031392, 2018). "TRIM3 could be a utilized as a diagnostic biomarker and therapeutic target for gastric cancer." (PMID 30031392, 2018). "TRIM3 expression is decreased in several human cancers, including gastric cancer, colon cancer and liver cancer." (PMID 35392925, 2022). "TRIM3 were reported to be decreased in several human cancers, such as gastric cancer, colon cancer and liver cancer." (PMID 33292295, 2020). "TRIM3 plays a role as tumor inhibition in gastric cancer, and TRIM3 knockdown can promote the growth and metastasis of gastric cancer by regulating stem cell factor and EMT regulator." (PMID 35006428, 2020). "For example, the delivery of tripartite motif-containing protein 3 (TRIM3) using gastric cancer-derived exosomes successfully suppressed the proliferation, migration, and metastasis of gastric cancer." (PMID 33028046, 2020). "We found that TRIM3 was detectable in 15% (3/20) of the gastric cancer tissues and 75% (15/20) of adjacent control tissues." (PMID 30031392, 2018). "We then conducted immunohistochemistry (IHC) to examine TRIM3 expression in 20 pairs of gastric cancer tissues and adjacent control tissues." (PMID 30031392, 2018). "To determine the effects of TRIM3-overexpressing exosomes on the tumorigenicity and metastasis of gastric cancer, we conducted xenograft tumor and peritoneal metastasis models in nude mice." (PMID 30031392, 2018). "To demonstrate that the decreased expression of exosomal TRIM3 is involved in gastric cancer progression, we overexpressed TRIM3 in gastric cancer cells and extracted the TRIM3-overexprressing exosomes from the transfected cells." (PMID 30031392, 2018). "The effects of TRIM3-overexpressing exosomes on gastric cancer growth and metastasis in vitro and in vivo were also evaluated." (PMID 30031392, 2018). "We demonstrated that TRIM3 overexpression reduced while TRIM3 knockdown promoted the growth and metastasis of gastric cancer in vitro and in vivo through the regulation of stem cell factors and EMT regulators." (PMID 30031392, 2018). "The expression of TRIM3 was upregulated in exosomes from TRIM3-overexpressing gastric cancer cells (P < 0.001) as detected by qRT-PCR and western bolt." (PMID 30031392, 2018). "TRIM3 overexpression inhibited while TRIM3 knockdown promotedthe growth and metastasis of gastric cancer through the regulation of stem cell factors and EMT regulators." (PMID 30031392, 2018). "Taken together, these results suggest that TRIM3 downregulation enhances gastric cancer growth and metastasis in vivo." (PMID 30031392, 2018). "The results showed that the expression of TRIM3 in exosomes from the serum of gastric cancer patients was much lower than that from the healthy controls, which was further confirmed by western blot assay." (PMID 30031392, 2018). "We found that the expression levels of TRIM3 mRNA and protein were decreased in gastric cancer tissues compared to the matched control tissues." (PMID 30031392, 2018). "We found that the expression of TRIM3 was lower in gastric cancer tissues than the paired control tissues in most cases." (PMID 30031392, 2018). "To further confirm the direct effect of miR-20a on TRIM3, we transfect miR-20a-mimics and miR-20a-inhibitor into gastric cancer cell lines." (PMID 30031392, 2018). "The growth and migration abilities of gastric cancer cells with TRIM3 overexpression or knockdown in vitro were evaluated by colony formation assay and transwell migration assay." (PMID 30031392, 2018). "We found that TRIM3 protein level was decreased in the serum exosomes of gastric cancer patients compared to that in healthy controls." (PMID 30031392, 2018).
gastric cancer (continued). "We performed ELISA to detect TRIM3 expression in exosomes that were extracted from 80 pairs of gastric cancer patients and healthy controls." (PMID 30031392, 2018). "Immunohistochemistry was used to detect TRIM3 expression in gastric cancer tissues and their matching adjacent tissues." (PMID 30031392, 2018). "We next determined the expression of TRIM3 in gastric cancer tissues and adjacent control tissues by using real-time quantitative reverse transcription PCR (qRT-PCR)." (PMID 30031392, 2018). "The results of western blot assay showed that TRIM3 expression was increased in the gastric cancer cells incubated with the TRIM3-overexpressing exosomes." (PMID 30031392, 2018). "The effects of TRIM3 overexpression or knockdown on gastric cancer growth and metastasis in vivo were investigated by using subcutaneous xenograft tumor and peritoneal metastasis mouse model." (PMID 30031392, 2018). "The expression of TRIM3 in exosomes from the serum of gastric cancer patients and healthy controls was assessed by ELISA and western blot." (PMID 30031392, 2018). "We found that TRIM3 inhibited gastric cancer growth and metastasis through the regulation of stem cell factors and EMT regulators, indicating that TRIM3 also plays tumor suppressive roles in gastric cancer." (PMID 30031392, 2018). "The tumor suppressive role of TRIM3 in gastric cancer and the presence of TRIM3 in exosomes led us to explore the possibility of delivering TRIM3 by exosomes to treat gastric cancer." (PMID 30031392, 2018). "We overexpressed TRIM3 in gastric cancer cells and collected the TRIM3-overexpressing exosomes and incubated gastric cancer cells with the TRIM3-overexpressing exosomes." (PMID 30031392, 2018). "Notably, a contrasting conclusion about TRIM3 is presented by another study, indicating that mRNA and protein levels of TRIM3 were decreased in clinical gastric cancer tissues." (PMID 39768197, 2024). "Moreover, engineered exosomes have been widely used to deliver certain drugs for disease treatment, such as the use of exosome-mediated TRIM3 delivery for gastric cancer or miRNA-401 for anti-HSV-1 virus infection." (PMID 35464963, 2022). "In addition, the levels of TRIM3 protein in the serum exosomes of gastric cancer patients were lower than that in healthy controls." (PMID 30031392, 2018). "The level of TRIM3 was negatively correlated with that of miR-20a in gastric cancer tissues." (PMID 30031392, 2018). "Taken together, our findings suggest that exosomal TRIM3 may serve as a biomarker for gastric cancer diagnosis and the delivery of TRIM3 by exosomes may provide a new avenue for gastric cancer therapy." (PMID 30031392, 2018). "We found that TRIM3 was significantly downregulated in gastric cancer tissues." (PMID 30031392, 2018). "TRIM3 was overexpressed in gastric cancer cells by transient transfection." (PMID 30031392, 2018). "We found that the TRIM3-overexpressing exosomes could be internalized into the gastric cancer cells." (PMID 30031392, 2018). "To investigate whether TRIM3 downregulation could promote gastric cancer growth and metastasis in vivo, we used the MGC-803 cells transfected with TRIM3 siRNA to establish subcutaneous tumor xenograft and peritoneal metastasis models in nude mice." (PMID 30031392, 2018). "We next tested the effects of TRIM3-overexpressing exosomes on gastric cancer cells." (PMID 30031392, 2018). "We next wanted to know whether TRIM3 downregulation also influenced the metastatic potential of gastric cancer cells in vivo." (PMID 30031392, 2018). "Altogether, these results suggest that TRIM3 plays a suppressive role in gastric cancer growth." (PMID 30031392, 2018). "We next verified the expression of TRIM3 in gastric cancer tissues and serum exosomes." (PMID 30031392, 2018). "Altogether, these results suggest that TRIM3-overexpressing exosomes could transfer TRIM3 to gastric cancer cells, which inhibit gastric cancer growth and metastasis in vivo." (PMID 30031392, 2018).
gastric cancer (continued). "We next wanted to know whether TRIM3 overexpression also influenced the metastatic potential of gastric cancer cells in vivo." (PMID 30031392, 2018). "Exosomal TRIM3 could inhibit gastric cancer growth and metastasis in vitro and in vivo, suggesting that exosomes-mediated transfer of TRIM3 might serve as a new strategy for gastric cancer therapy." (PMID 30031392, 2018). "TRIM3 functions as a tumor suppressor by inhibiting gastric cancer growth and metastasis." (PMID 30031392, 2018). "We detected the expression of TRIM3 in gastric cancer cells and gastric epithelial cells." (PMID 30031392, 2018). "However, more studies are warranted to clarify the molecular mechanism responsible for the roles of TRIM3 in gastric cancer." (PMID 30031392, 2018). "Our findings suggest that TRIM3 expression is downregulated in gastric cancer." (PMID 30031392, 2018). "Moreover, we demonstrated that exosomes-mediated delivery of overexpressed TRIM3 could suppress gastric cancer growth and metastasis in vitro and in vivo." (PMID 30031392, 2018). "Moreover, exosomes-mediated delivery of TRIM3 protein could suppress gastric cancer growth and metastasis in vitro and in vivo." (PMID 30031392, 2018). "In gastric cancer, similar to prostate cancer, EGFR was of a higher level in exosomes, and recently, tripartite motif-containing 3 (TRIM3) was found to be decreased in the serum of gastric cancer patients, making exosomal TRIM3 a potential biomarker of gastric cancer." (PMID 33922480, 2021). "Tripartite motif-containing 3 (TRIM3) and gastrokine 1 (GKN1) were found to be downregulated in plasma exosomes in gastric cancer (GC) compared with those in healthy controls, so these factors are thought to be novel biomarkers for GC diagnosis and therapeutic targets." (PMID 38814362, 2024). "However, the roles of TRIM3 in gastric cancer have not been well characterized." (PMID 30031392, 2018). "Interestingly, despite increased levels of TRIM3 and TRIM16 in human gastric cancer tissues, they showed a negative correlation with the β-catenin levels and some of its downstream targets in vitro, such as BCL2, suggesting their tumor-suppressing function." (PMID 39768197, 2024).
glioblastoma (12 papers, 2015 to 2024). The most malignant astrocytic tumor (WHO grade IV). "It has been reported that the loss of TRIM3 gene promotes the development and progression of glioblastomas, while overexpression reduces the tumorigenicity of GBM." (PMID 30031392, 2018). "In experiments utilizing orthotopic tumor-bearing nude mice, it was viewed that mice engrafted with U87-TRIM3 cells exhibited a longer median survival time, indicating that TRIM3 expression exerts an inhibitory effect on glioblastoma in vivo." (PMID 38411731, 2024). "TRIM3 is identified as the candidate tumor suppressor gene in glioblastomas, cervical cancer, esophageal squamous cell carcinoma, and hepatocellular carcinoma." (PMID 36894560, 2023). "TRIM3 is highly enriched in neurons and reported to abnormally express in several human cancers, including glioblastoma and hepatocellular carcinoma." (PMID 36894560, 2023). "In human glioblastoma explanted cultures mutant for TRIM3, transport of active NOTCH1 (NICD) is perturbed, resulting in enhanced tumor growth." (PMID 37549261, 2023). "For example, tripartite motif containing 3 (TRIM3) at 11p15.5 is lost in ~20% of glioblastomas (GBM)." (PMID 33450833, 2021). "Reduced expression of tripartite motif-containing 3 (TRIM3) has been reported to be involved in the pathogenesis of human glioblastoma." (PMID 28950898, 2017). "Among these, TRIM3, a prototypical E3 ubiquitin ligase, assumes a vital role in glioblastoma." (PMID 38411731, 2024). "The mammalian ortholog of brat, TRIM3, has similarly been shown to reduce MYC and promote differentiation in human glioma cell lines, while a reduced TRIM3 expression has been reported in glioblastoma and is associated with poor survival." (PMID 33092025, 2020). "Similarly, the mammalian homologue TRIM3 has been reported as a tumor suppressor in human glioblastoma (GBM), a highly malignant human brain tumor, through its suppression on Myc." (PMID 26492166, 2015). "They demonstrated TRIM3's inhibitory effect on c-myc transcriptional activity and expression levels in glioblastoma by employing the c-myc-driven luciferase reporter gene in U87 MG and LN 229 GBM cell lines." (PMID 38411731, 2024). "The human Brat orthologue, TRIM3, is also a brain tumour suppressor demonstrated by repression of patient-derived glioblastoma (GBM) stem cells (GSCs) tumourigenic potential and growth of intracranial xenografted GBM cells in mice." (PMID 38225354, 2024).